ZBTB40 (zinc finger and BTB domain containing 40)
Description:
May be involved in transcriptional regulation.
Synonyms: KIAA0478; ZNF923
Tractability: PROTAC: UniProt records ubiquitination sites on it; ubiquitination databases record sites on it.
Target class: Transcription factor
Gene: Protein-coding gene on chromosome 1 (22,428,838 to 22,531,157, forward strand). Ensembl gene ENSG00000184677.
Subcellular location: Nucleus
Subcellular location (Human Protein Atlas): Nucleoplasm
Gene Ontology:
Molecular function: protein binding; DNA-binding transcription factor activity, RNA polymerase II-specific
Biological process: DNA damage response; bone mineralization; regulation of transcription by RNA polymerase II
Cellular component: nucleus
Genetic constraint (gnomAD): Loss-of-function variants: 60 observed, 123.47 expected, observed/expected ratio (o/e) 0.49, 90% interval 0.39 to 0.6. The upper end of that interval is the gene's LOEUF score, 0.6, which puts it in group 2 of 6, group 1 being the genes least tolerant of losing a copy. Missense variants: 1,287 observed, 1,582 expected, observed/expected ratio (o/e) 0.81, 90% interval 0.78 to 0.85. Synonymous variants: 525 observed, 611.4 expected, observed/expected ratio (o/e) 0.86, 90% interval 0.8 to 0.92.
Homologues: Orthologues: chimpanzee ZBTB40 (99% identical), macaque ZBTB40 (96% identical), pig ZBTB40 (87% identical), dog ZBTB40 (86% identical), guinea pig ZBTB40 (84% identical), rabbit ZBTB40 (83% identical), rat Zbtb40 (79% identical), mouse Zbtb40 (79% identical), tropical clawed frog zbtb40 (55% identical), zebrafish zbtb40 (35% identical), Drosophila melanogaster CG44002 (8% identical), Drosophila melanogaster CG15336 (5% identical).
Diseases named in the same sentence as ZBTB40 in open-access papers:
ZBTB40 is named in the same sentence as 6 diseases in open-access papers, as found by Europe PMC text mining. Sharing a sentence is not in itself a finding about the gene and the disease. The quoted sentences say what the papers report.
osteoporosis (3 papers, 2011 to 2025). A condition of reduced bone mass, with decreased cortical thickness and a decrease in the number and size of the trabeculae of cancellous bone (but normal chemical composition), resulting in increased fracture incidence. "ZBTB40’s involvement is particularly pronounced in IBD-related osteoporosis." (PMID 41264632, 2025). "Recent studies have reported that Zbtb40 is likely a candidate gene for mineralized nodule formation, suggesting that ZBTB40 may be a new target for future treatment of osteoporosis." (PMID 37174664, 2023). "The results of the analysis on BMD and osteoporosis were subsequently structured, uncovering four shared genes in IBD: ZBTB40, RP1-135L22.1, RSPO3, and RP11-103J8.1." (PMID 41264632, 2025). "Current findings suggest that ZBTB40 may be a key molecular link between IBD, BMD regulation, and osteoporosis development, thus presenting substantial clinical translational potential." (PMID 41264632, 2025). "Furthermore, ZBTB40 is proposed to regulate BMD by affecting vitamin D metabolism and calcium ion homeostasis, thus offering novel mechanistic insights into secondary osteoporosis observed in IBD patients." (PMID 41264632, 2025).
male infertility (2 papers, 2023). The inability of the male to effect fertilization of an ovum after a specified period of unprotected intercourse. "Here, we have demonstrated, for the first time, that a loss of ZBTB40 function leads to abnormalities in the morphological and phenotypic characteristics of mouse spermatocytes and spermatids as well as male infertility." (PMID 37174664, 2023). "Collectively, our study indicates that Zbtb40 deficiency leads to morphological and phenotypic abnormalities of spermatocytes and spermatids, as well as telomere dysfunction, which causes male infertility." (PMID 37174664, 2023). "Our results implicate that ZBTB40 deficiency leads to morphological and phenotypic abnormalities of spermatocytes and spermatids and causes male infertility." (PMID 37174664, 2023). "Significantly, our loss-of-function study suggests that the Zbtb40 knockout mice show male infertility, and they assume morphologically defective sperm heads, flagella, and acrosome biogenesis." (PMID 37174664, 2023). "We constructed Zbtb40 knockout mice, and notably, we have demonstrated, for the first time, that Zbtb40 deficiency results in abnormal spermatogenesis and male infertility." (PMID 37174664, 2023). "In the present study, we found that a loss of function of ZBTB40 resulted in male infertility." (PMID 37174664, 2023). "To this end, we hypothesized that the loss of ZBTB40 function may result in abnormal spermatogenesis and male infertility." (PMID 37174664, 2023). "We have demonstrated, for the first time, that a Zbtb40 knockout leads to abnormal morphological and phenotypic characteristics of mouse spermatocytes and spermatids and eventual male infertility." (PMID 37174664, 2023). "The testis and cauda epididymis body weights of Zbtb40+/− mice were significantly decreased, and the sperm of Zbtb40+/− mice were assumed as abnormal flagellum acrosome, which leads to male infertility." (PMID 37454741, 2023). "It is of great importance to probe the association between the mutations of the ZBTB40 gene and male infertility in humans, which could provide novel biomarkers and targets for male infertility diagnosis and gene therapy." (PMID 37174664, 2023).
Azoospermia (1 paper, 2023). Absence of any measurable level of sperm,whereby spermatozoa cannot be observed even after centrifugation of the semen pellet. "In this study, we have revealed that ZBTB40, an autosomal gene located in 1p36.12 in humans, is expressed specifically in mouse spermatocytes, and significantly, loss of Zbtb40 led to severe azoospermia and multiple morphological abnormalities of sperm." (PMID 37174664, 2023). "Furthermore, a ZBTB40 mutation was associated with non-obstructive azoospermia." (PMID 37174664, 2023).
endometriosis (1 paper, 2021). The growth of functional endometrial tissue in anatomic sites outside the uterine body. "The strongest burden statistic was on chromosome 1p36 (the region encompassing ZBTB40, WNT4 and CDC42), with two types of ovarian cancer (clear cell carcinoma and high-grade serous carcinoma, while epidemiologically, endometriosis does not constitute a risk factor for this last type of cancer)." (PMID 34298916, 2021).
inflammatory bowel disease (1 paper, 2025). A spectrum of small and large bowel inflammatory diseases of unknown etiology. "Variants in ZBTB40 have been associated with inflammatory bowel disease and low bone density and WNT4 with sex-determination developmental disorders." (PMID 39844285, 2025).
promyelocytic leukemia (1 paper, 2023). "The results also show that ZBTB40 is associated with ALT-associated promyelocytic leukemia nuclear bodies, and the loss of ZBTB40 induces the accumulation of the ALT-associated promyelocytic leukemia nuclear bodies in U2OS cells." (PMID 37454741, 2023).